BMP2 (bone morphogenetic protein 2)
Diseases named in the same sentence as BMP2 in open-access papers (continued):
Sharing a sentence is not in itself a finding about the gene and the disease.
lymph node metastasis (4 papers, 2014 to 2022). "High BMP-2 expression levels were significantly associated with the occurrence of lymph node metastases and tumor stage (P < 0.05)." (PMID 24946687, 2014). "Logistic regression analysis indicated that the relative expression level of BMP-2 mRNA was a risk factor for lymph node metastasis in patients with NSCLC." (PMID 24946687, 2014). "Our results revealed that samples derived from patients with lymph node metastasis had significantly higher BMP2 expression levels than samples derived from patients without lymph node metastasis (p-value = 0.0193)." (PMID 36175474, 2022). "As shown, high expression of BMP2 was significantly correlated with larger tumor size (P = 0.038), lymph node metastasis (P = 0.008), advanced clinical stages (P = 0.000), distant metastasis rate at diagnosis (P=0.01) and bone metastasis (P=0.028)." (PMID 28455969, 2017). "Our analyses found significant correlations between BMP-2 expression and lymph node metastasis, TNM stage, tumor stage, and survival time." (PMID 24946687, 2014). "Additionally, in samples derived from patients with lymph node metastasis, higher BMP2 expression levels correlated with higher expression levels of the mesenchymal marker vimentin." (PMID 36175474, 2022). "Furthermore, we found that BMP-2 expression was related to lymph node metastasis, tumor stage, and survival time." (PMID 24946687, 2014). "In a study of 178 gastric tumor biopsies, the expression of BMP-2 and Matrix metallopeptidase (MMP)-9 showed a significant positive correlation with lymph node metastasis and a poor prognosis." (PMID 34001012, 2021). "In contrast, approximately 26% samples with lymph node metastasis and 73% samples without lymph node metastasis in low BMP2 expression group." (PMID 36175474, 2022). "There are approximately 60% samples with lymph node metastasis and 40% samples without lymph node metastasis in moderate and high BMP2 expression group." (PMID 36175474, 2022).
medulloblastoma (4 papers, 2013 to 2020). A malignant, invasive embryonal neoplasm arising from the cerebellum. "Yet, different mechanisms through which retinoic acid induces apoptosis in medulloblastoma were reported, including expression of BMP2 or expression of FAS and its ligand FASL." (PMID 32585856, 2020). "BMP2 is known to be involved in development and differentiation of granule neuron precursor cells (GNCPs), one potential cell of origin for medulloblastoma." (PMID 24252778, 2013). "Based on our data demonstrating that apoptosis is induced even in DAOY cells following KDM1A knockdown, we suggest that KDM1A inhibition can circumvent the blockade of BMP2-mediated apoptosis in medulloblastoma cells incapable of responding to retinoids." (PMID 24252778, 2013). "We suggest that BMP2 upregulation in response to KDM1A knockdown could be an intermediate to inducing apoptosis in medulloblastoma cells, but acting via routes different from sonic hedgehog pathway inhibition." (PMID 24252778, 2013). "However, in their study BMP2-mediated apoptosis was restricted to cells responsive to retinoids, thus, excluding this mechanism of action in a variety of medulloblastoma-derived cell lines, including DAOY." (PMID 24252778, 2013). "We show here that BMP2 was upregulated in medulloblastoma cell lines following KDM1A knockdown." (PMID 24252778, 2013). "BMP2 activation contributes to cell cycle arrest, apoptosis or differentiation of GNPCs, which are considered to be the cells of origin for SHH driven medulloblastomas." (PMID 24252778, 2013). "BMP2 has also been previously shown to be involved in the normal development and differentiation of GNPCs, the cells of potential origin of SHH medulloblastoma subtypes." (PMID 24252778, 2013). "BMP-2 and -4 signaling antagonizes SHH-dependent proliferation by inducing the irreversible differentiation of cerebellar granule neuron progenitors (GNPs) and of medulloblastoma cells." (PMID 23527084, 2013). "Thus, by downregulating BMP2, SHH group medulloblastomas might escape from apoptotic signals or maintain an undifferentiated phenotype." (PMID 24252778, 2013).
metastatic tumor (4 papers, 2011 to 2025). "BMP2 alteration was associated with tumor metastasis status and metastatic tumor indicators in TCGA database and correlated with Prediction Analysis of Microarray 50 (PAM50)-based molecular subtype and tumor stage in the METABRIC database." (PMID 40936753, 2025). "In addition, we found that tumor cells expressed higher levels of BMP2, N-cadherin, Vimentin and p-SMAD1/5 in the shLacZ group than in the shBMP2 group by IHC both in primary tumors (right lung) and metastatic tumors (left lung)." (PMID 36175474, 2022).
neuroblastoma (4 papers, 2012 to 2022). Neuroblastoma (NB) is the most common solid, extracranial childhood tumor. "NBL1 is an antagonist of BMP2, also known as neuroblastoma (DAN), a tumor suppressor that plays essential roles in numerous biological functions." (PMID 35487890, 2022). "Our transcriptomic analysis did not support activation of DLX2, BRN3A, or NEUROD6 genes as being involved in the BMP4-induced phenotypes of neuroblastoma cells, as previously suggested by studies using BMP2." (PMID 32210188, 2020). "BMP2 induced neural differentiation in mouse neuroblastoma cells by increasing the expression of neurogenic transcription factors Dlx2, Brn3a, and NeuroD6." (PMID 32210188, 2020). "Grem1, which is a member of the DAN (differential screening-selected gene aberrative in neuroblastoma) family of secreted BMP antagonists, selectively binds to BMP-2, -4, and -7 to exert biological functions." (PMID 35440754, 2022).
oral cancer (4 papers, 2011 to 2025). "Therefore, it is inevitable to establish methods that could accurately evaluate whether BMP-2 exogenously injected for oral hard tissue regeneration is associated with oral cancer." (PMID 25271422, 2014). "Considering that ID3 expression, which is a target gene of both Smad1/5/9 and p38, was increased by CCN6 combined with BMP2, and that production of CCN6 and BMP2 increased in the cells before EMT, it is suggested that CCN6 combined with BMP2 suppresses EMT of oral cancer cells in primary lesions." (PMID 37590989, 2023). "Future studies will be necessary to determine whether combined blockage of these proteins will provide protection against BMP-2-induced oral cancer progression." (PMID 25271422, 2014). "However, findings of these previous studies are insufficient for revealing the role of BMP-2 and its mechanism related to oral cancer progression." (PMID 25271422, 2014). "Screening of the data revealed eight TRGs (TGFB3, LTBP2, BMP2, TGFB1, ACVR1, CDK9, SLC20A1, and SMURF2) with non-zero coefficients, indicating their association with the prognosis of oral cancer patients." (PMID 38698292, 2025). "The effect of fibroblasts on oral cancer progression related to BMP-2 has not yet been considered, although stromal fibroblasts are known as important and main host cell types in tumor microenvironments." (PMID 25271422, 2014). "Considering this clinical situation, we developed an invitro system that combined BMP-2 and pre-existing oral cancer cells with or without fibroblasts." (PMID 25271422, 2014). "Therefore, in this study, we assumed the situation that clinicians would not detect or disregard the signs of pre-existing oral cancer cells before BMP-2 treatment for bone-defective areas." (PMID 25271422, 2014).
otosclerosis (4 papers, 2013 to 2023). Formation of spongy bone in the labyrinth capsule which can progress toward the stapes (stapedial fixation) or anteriorly toward the cochlea leading to conductive, sensorineural, or mixed hearing loss. "Bone morphogenetic proteins 2 and 4 (BMP2 and BMP4), which are members of the TGFB superfamily and play important roles in several stages of bone metabolism, have also been associated with otosclerosis susceptibility." (PMID 37647735, 2023). "Here, we genotyped eight previously associated variants in the following six candidate genes: RELN, BMP2, FGF2, COL1A1, TGFB1, and PPP2R5B in a large UK case–control otosclerosis cohort (n = 748)." (PMID 29728750, 2018). "A study investigating rare and common variations in BMP2 and BMP4 did not identify an association between common variants and otosclerosis." (PMID 37647735, 2023). "It has been reported that COL1A1, BMP2, BMP4, TGFB1, and RELN genes may also contribute to the development of otosclerosis." (PMID 23864959, 2013). "Various members of this family including TGF-β1 and bone morphogenetic proteins BMP2 and BMP4 have been associated with otosclerosis in some candidate gene association studies but not all; however, a precise role for this gene family in development of otosclerosis has not been defined." (PMID 27056980, 2016).
rectal cancer (4 papers, 2016 to 2025). A primary or metastatic malignant neoplasm that affects the rectum. "Another study shown that the excessive expression of BMP-2 stimulates the formation of heterotopic ossification in rectal cancer." (PMID 39932915, 2025). "Another research showed overexpression of BMP-2 promote HO form in rectal cancer." (PMID 33391181, 2020). "For rectal cancer, the interaction P-values of <0.05 were observed for CYP24A1 (vitamin D metabolism) and BMP2 (TGF signaling)." (PMID 31434255, 2019).
sarcopenia (4 papers, 2017 to 2025). Progressive decline in muscle mass due to aging which results in decreased functional capacity of muscles. "Results here reported, highlighting the role of BMPs and myostatin pathways in physio-pathogenesis of human sarcopenia, allow us to propose human recombinant BMP-2/7 and anti-myostatin antibodies as a possible therapeutic option for the sarcopenia." (PMID 28202082, 2017). "Results here reported, highlighting the role of BMPs and myostatin pathways in physio-pathogenesis of human sarcopenia, allow us to propose human recombinant BMP-2/7 and anti-myostatin antibodies as a possible therapeutic option for sarcopenic patients." (PMID 28202082, 2017). "MiR-451a and miR-421-3p, the two miRNAs that were observed to be differently expressed in sarcopenia, thus regulate two proteins (SNAP-25 and BMP-2) related to muscle function." (PMID 34289870, 2021).
Stroke (4 papers, 2011 to 2021). Sudden impairment of blood flow to a part of the brain due to occlusion or rupture of an artery to the brain. "Bone marrow MSCs increase BMP2/4 expression in ischemic astrocytes, enhancing subventricular progenitor cell gliogenesis by activating relevant signaling pathways and thus improving functional recovery after stroke." (PMID 33546766, 2021). "Although BMP2 is upregulated after cerebral ischemia, its function as an endogenous neuroprotectant is controversial since recombinant soluble Noggin, an antagonist of BMP2, BMP4 and BMP7, demonstrates neuroprotective effects in models of stroke." (PMID 24618040, 2014).
acute myeloid leukemia (3 papers, 2021 to 2023). Acute myeloid leukemia (AML) is a group of neoplasms arising from precursor cells committed to the myeloid cell-line differentiation. "Elevated BMP2 in Acute Myeloid Leukemia (AML) patients induces the production of CD25+CD127lowVδ2+ T cells (named Reg-Vδ2)." (PMID 38077392, 2023). "Notably, BMP2 and BMP4 are overexpressed in the bone marrow of Acute Myeloid Leukemia (AML) patients, supporting the aggressive clonal malignancy through excessive proliferation of immature cells blocked in their differentiation process." (PMID 35047500, 2021).
aortic valve disease (3 papers, 2021 to 2025). "Bmp2 is a key pathway activated and causally linked to calcific aortic valve disease in animal models." (PMID 34294700, 2021).
apical periodontitis (3 papers, 2018 to 2024). "Recently, CHISP were reported to induce bone formation of apical periodontitis and periapical bone regeneration in vivo due to expression of BMP-2 in rats." (PMID 29619378, 2018). "The aim of this research was to evaluate radiographically and histologically the potential of immature dog’s teeth with apical periodontitis to regenerate after application of MSNs scaffolds with/without BMP-2." (PMID 39026199, 2024).
astrocytomas (3 papers, 2020 to 2025). "Compared to G2 tumors, high-grade astrocytomas (G3 and G4) exhibited elevated levels of SKIL, SMAD1, SMAD3, BMP2, and MAPK1, with most differences reaching statistical significance (p < 0.05)." (PMID 40869118, 2025). "In this study, we present multi-level evidence demonstrating that key mediators of the TGF-β signaling pathway—SKIL, BMP2, SMAD1, SMAD3, SMAD4, and MAPK1—are consistently upregulated in high-grade astrocytomas." (PMID 40869118, 2025). "Indeed, the mining of two databases indicated significant upregulation of BMP2 in grade II/III oligodendrogliomas and astrocytomas compared to nontumoral tissues; BMP4 was overexpressed in oligodendrogliomas in one database." (PMID 33925547, 2021).
atrial fibrillation (3 papers, 2022 to 2024). A disorder characterized by an electrocardiographic finding of a supraventricular arrhythmia characterized by the replacement of consistent P waves by rapid oscillations or fibrillatory waves that vary in size, shape and timing and are accompanied by an irregular ventricular response. "Moreover, a highly significant increase of BMP-2 was observed in a small subgroup of CKD patients with atrial fibrillation and 25-OH-cholecalciferol deficiency." (PMID 36613483, 2022). "A small subgroup of CKD patients with atrial fibrillation (n = 5) showed a significant BMP-2/BMP-7 imbalance with significantly higher (p < 0.05) BMP-2 and lower (p < 0.07, non-significant) BMP-7 concentrations compared with CKD patients without atrial fibrillation." (PMID 36613483, 2022).
benign lung tumors (3 papers, 2013 to 2014). "BMP-2 is expressed approximately 17 fold higher in NSCLC compared to normal lung or benign lung tumors." (PMID 23593444, 2013). "BMP-2 is highly overexpressed in human NCSLC compared with normal lung tissue and benign lung tumors, and high BMP-2 levels enhanced tumor cell migration and invasion, thereby promoting tumor growth." (PMID 24946687, 2014). "BMP2 is highly overexpressed in 98% of NSCLC with little expression in paired normal lung tissue and benign lung tumors." (PMID 24160469, 2013).
bladder cancer (3 papers, 2018 to 2025). "Mouse experiments confirmed that inhibiting BMP2 can suppress tumor angiogenesis and growth in bladder cancer." (PMID 40552583, 2025). "In conclusion, our results demonstrate that BMP2 enhances tumor growth and angiogenesis in a mouse bladder cancer model, likely through the induction of WNT5A and modulation of endothelial cell behavior." (PMID 40552583, 2025). "To investigate the role of BMP2 in bladder cancer progression, we treated C57BL/6J mouse bladder orthotopic tumor models with BMP2 and its small molecule inhibitor, Dorsomorphin." (PMID 40552583, 2025). "Targeting BMP2 suppresses tumor angiogenesis and growth, highlighting the therapeutic potential of CAF modulation in bladder cancer." (PMID 40552583, 2025). "Considering that BMP2 and BMP7 could promote the proliferation and migration of bladder cancer, we try to confirm whether BMP9 plays a role in the development of bladder cancer." (PMID 29642505, 2018).
bladder urothelial carcinoma (3 papers, 2017 to 2021). "Expression of BMP2 was significantly higher in bladder urothelial carcinoma cases with bone metastasis." (PMID 28455969, 2017). "In addition, studies have reported that the expression of MED19 was positively correlated with the expression of bone morphogenetic protein 2 (BMP2) in bladder urothelial carcinoma bone metastasis and invasion." (PMID 35047403, 2021).
bone metastasis (3 papers, 2017 to 2025). Transfer of a neoplasm from its primary site to bones. "This study identified 74 DEGs between BRCA samples with or without bone metastasis, and 5 important DEGs were finally filtered, namely, MMP9, ITGB3, BMP2, CCL2, and PROM1." (PMID 36193308, 2022).
bone tumor (3 papers, 2020 to 2024). "As numerous cell types were growing within the metastatic bone tumours, we investigated the expression of BMP2 in bone metastasis through immunofluorescence assay." (PMID 32750747, 2020). "BMP signaling was activated in the metastatic bone tumor of Lewis lung cancer in mice, and BMP2 signaling activation could enhance the bone metastasis of Lewis lung cancer, leading to poor prognosis." (PMID 34394080, 2021). "Enhanced mechanical strength, excellent photothermal effect, osteogenesis of rBMSCs rabbit bone marrow stromal cells, increased expression levels of BMP2, RUNX2 and COL 1 osteogenic genes, inhibition of bone tumor and bone regeneration effects." (PMID 38791452, 2024).
Cirrhosis (3 papers, 2012 to 2025). A chronic disorder of the liver in which liver tissue becomes scarred and is partially replaced by regenerative nodules and fibrotic tissue resulting in loss of liver function. "BMP2, BMPR1A, FGF7, FGFR2 and ID3 were more highly expressed in cirrhosis than HCC, while the BMP inhibitors were more highly expressed in tumors." (PMID 23667740, 2012). "In the tumors, most of the proliferation promoters had expression values similar to that of normal tissue (which is sufficient to induce proliferation in the absence of active BMP2), including those that were down-regulated in cirrhosis." (PMID 23667740, 2012). "BMP2, its receptors, and BMP inhibitors are all differentially expressed in cirrhosis and HCC." (PMID 23667740, 2012).
dentinogenesis imperfecta (3 papers, 2021 to 2025). Dentinogenesis imperfecta (DGI) is a hereditary dentin defect characterized by abnormal dentin structure resulting in abnormal tooth development. "BMP2-deficient teeth display morphological features similar to dentinogenesis imperfecta (DGI), which is associated with mutations in the DMP1 and DSPP genes." (PMID 40133254, 2025). "Teeth lacking Bmp2 exhibit a morphology reminiscent of dentinogenesis imperfecta (DGI), associated with mutations in dentin matrix protein 1 (DMP1) and dentin sialophosphoprotein (DSPP) genes." (PMID 37790473, 2023). "Teeth with Bmp2 cKO mice display the similar phenotype of dentin defects to that of dentinogenesis imperfecta (DGI) in humans and mice, the most common dentin genetic diseases, showing retardation of tooth growth, abnormal dentin structure with wide predentin, and thin dentin." (PMID 35003201, 2021).
diabetic nephropathy (3 papers, 2013 to 2023). "Our previous study provided evidence supporting involvement of the BMP-2/Smad1/Runx2/Osterix signaling pathway in the development of vascular calcification in diabetic nephropathy rats." (PMID 29850574, 2018). "There has been interest in BMP antagonists for treating renal disease: for example, Gremlin, an antagonist of BMP2 and 4, may be protective of diabetic nephropathy in experimental models." (PMID 37816758, 2023).